DPM3 (dolichyl-phosphate mannosyltransferase subunit 3, regulatory)
Description:
Stabilizer subunit of the dolichol-phosphate mannose (DPM) synthase complex; tethers catalytic subunit DPM1 to the endoplasmic reticulum.
Synonyms: MGC34275; MGC125904; MGC125905; CDG1O; MDDGB15; MDDGC15
Tractability: Antibody: UniProt predicts a signal peptide or a membrane-spanning region. PROTAC: its protein half-life has been measured.
Gene: Protein-coding gene on chromosome 1 (155,139,886 to 155,140,595, reverse strand). Ensembl gene ENSG00000179085.
Subcellular location: Endoplasmic reticulum membrane
Pathways (Reactome):
Disease: Defective DPM1 causes DPM1-CDG; Defective DPM2 causes DPM2-CDG; Defective DPM3 causes DPM3-CDG; Maturation of DENV proteins
Metabolism of proteins: Synthesis of dolichyl-phosphate mannose
Gene Ontology:
Molecular function: enzyme activator activity; protein binding; protein-membrane adaptor activity
Biological process: dolichol phosphate mannose biosynthetic process; dolichyl monophosphate biosynthetic process; protein O-linked glycosylation via mannose; glycoprotein biosynthetic process
Cellular component: dolichol-phosphate-mannose synthase complex; endoplasmic reticulum; endoplasmic reticulum membrane; membrane
Genetic constraint (gnomAD): Loss-of-function variants: 7 observed, 9.6 expected, observed/expected ratio (o/e) 0.73, 90% interval 0.41 to 1.36. That is too few expected variants to judge how well the gene tolerates losing a copy. Missense variants: 108 observed, 123.25 expected, observed/expected ratio (o/e) 0.88, 90% interval 0.75 to 1.03. Synonymous variants: 41 observed, 60.1 expected, observed/expected ratio (o/e) 0.68, 90% interval 0.53 to 0.88.
Gene-disease validity (ClinGen):
ClinGen rates the evidence that DPM3 causes each of these diseases.
DPM3-congenital disorder of glycosylation (autosomal recessive): Moderate. DPM3-CDG is an extremely rare form of CDG syndrome characterized clinically in the single reported case by muscle weakness, waddling gait and dilated cardiomyopathy.
Homologues: Orthologues: chimpanzee DPM3 (100% identical), pig DPM3 (93% identical), mouse Dpm3 (90% identical), rat Dpm3 (90% identical), guinea pig DPM3 (88% identical), tropical clawed frog dpm3 (65% identical), zebrafish dpm3 (55% identical), Drosophila melanogaster Dpm3 (40% identical), Caenorhabditis elegans dpm-3 (28% identical).
Diseases named in the same sentence as DPM3 in open-access papers:
DPM3 is named in the same sentence as 28 diseases in open-access papers, as found by Europe PMC text mining. Sharing a sentence is not in itself a finding about the gene and the disease. The quoted sentences say what the papers report.
Dystroglycanopathies (4 papers, 2018 to 2023). "Loss of function due to DPM3 gene mutations clinically results in a rare type of limb–girdle muscular dystrophy–dystroglycanopathy, presenting with progressive proximal muscle weakness and DCM." (PMID 37239976, 2023). "Pathogenic variants in DPM1 and DPM2 are associated with muscle–eye–brain (MEB) disease, whereas DPM3 variants have mostly been reported in patients with isolated muscle disease—dystroglycanopathy." (PMID 35932216, 2022). "Crucially, 15 of our 27 patients had suspected pathogenic variants in genes that were omitted from the study (DPM3, FKRP, GMPPB, ISPD and POMK), indicating that an unbiased approach must be sought to fully characterise dystroglycanopathies." (PMID 30060766, 2018).
prostate carcinoma (4 papers, 2018 to 2022). A carcinoma that arises from epithelial cells of the prostate gland. "Another report related to prostate tumor invasion pointed out DPM3 was a invasion suppressor using microarray expression analysis of the transcription levels in prostate cancer sublines." (PMID 33282554, 2020). "SNPs in the region of EFNA1, DPM3 and KRTCAP3 have previously been associated with prostate cancer risk and γ-glutamyl transferase (GGT), an indicator of liver disease." (PMID 29659830, 2018). "Moreover, AR-A may increase the invasion of prostate cancer PC3 cells and modulate secretion of HSP, NEP, DPM3/prostin-1." (PMID 31731466, 2019).
muscular dystrophy (3 papers, 2019 to 2024). Muscular dystrophy (MD) refers to a group of more than 30 genetic diseases characterized by progressive weakness and degeneration of the skeletal muscles that control movement. "Deficiency in DPM1 has been associated with CDG syndrome due to deficient protein N-glycosylation, whereas defect in DPM3 causes a muscular dystrophy associated with abnormal O-mannosylation of dystroglycan." (PMID 37152991, 2023). "DOLK‐CDG, DPM1‐CDG, DPM2‐CDG, and DPM3‐CDG are defects in the DPM synthesis showing both CDG‐I abnormalities and reduced O‐mannosylation of alpha‐dystroglycan (αDG), which leads to muscular dystrophy‐dystroglycanopathy." (PMID 31741824, 2019).
cardiomyopathy (2 papers, 2013 to 2018). A disease of the heart muscle or myocardium proper. "Cardiomyopathy has been detected in O-mannosylation defects and combined N-and O-linked glycosylation defects (DPM3-CDG), giving additional confirmation regarding the interplay of different glycosylation steps and the abnormal glycosylation of diverse proteins in heart, as a consequence." (PMID 22327749, 2013). "A homozygous DPM3 mutation (p.Leu85Ser) was first identified in an 11-year-old female with a mild LGMD, cardiomyopathy at 20 years of age and a stroke-like episode at 21 years of age." (PMID 30060766, 2018). "Interestingly, our identification of a patient with a homozygous DPM3 mutation (p.Leu44Pro) is the first description of such a patient without cardiomyopathy or central nervous system involvement." (PMID 30060766, 2018).
Alzheimer disease (1 paper, 2021). A progressive, neurodegenerative disease characterized by loss of function and death of nerve cells in several areas of the brain leading to loss of cognitive function such as memory and language. "DPM3 has also been shown to be downregulated in the entorhinal cortex of patients with Alzheimer’s disease." (PMID 34379632, 2021).
breast invasive carcinoma (1 paper, 2020). "Similarly, DPM3 gene was particularly highly expressed in breast invasive carcinoma (BRCA) (p = 1.62E−12), ESCA (p = 8.22E−10), LIHC (p = 1.11E−16) and glioblastoma multiforme (GBM) (p = 1.53E−05)." (PMID 33282554, 2020).
developmental delay (1 paper, 2022). "Here we report three unrelated Iranian families and one from Sri Lanka with five children presenting with congenital muscle weakness, developmental delay (DD)/intellectual disability (ID), and epilepsy due to an ultra‐rare homozygous missense DPM3 variant." (PMID 35932216, 2022). "We report three unrelated Iranian families and one from Sri Lanka with five children presenting with congenital muscle weakness, developmental delay/intellectual disability, epilepsy, and white matter abnormalities due to an ultra‐rare homozygous missense DPM3 variant." (PMID 35932216, 2022).
epilepsy (1 paper, 2022). A brain disorder characterized by episodes of abnormally increased neuronal discharge resulting in transient episodes of sensory or motor neurological dysfunction, or psychic dysfunction. "Hereby we describe five patients with a genetically confirmed homozygous variant in DPM3, presenting with muscle involvement along with WMA, DD/ID, and epilepsy." (PMID 35932216, 2022).
hepatoma (1 paper, 2020). "We evaluated DPM1, DPM2 and DPM3 expression levels in a panel of three cell lines: two hepatoma cells (HepG2 and SMMC-7721) and one normal liver cell line (QSG-7701)." (PMID 33282554, 2020).
Intellectual disability (1 paper, 2022). "Thus far, only one affected individual with compound heterozygous DPM3 variants presenting with myopathy, mild intellectual disability, seizures, and nonspecific white matter abnormalities (WMA) around the lateral ventricles has been described." (PMID 35932216, 2022).
limb-girdle muscular dystrophy (1 paper, 2010). Limb-girdle muscular dystrophy (LGMD) is a heterogeneous group of muscular dystrophies characterized by proximal weakness affecting the pelvic and shoulder girdles. "Less severe phenotypes include one form of congenital muscular dystrophy, MDC1C [OMIM 606612] and four forms of Limb girdle muscular dystrophy: LGMD 2I [OMIM 607155], LGMD 2K [OMIM 609308], LGMD 2M [OMIM 611588] and the variant due to DPM3 deficiency." (PMID 21203384, 2010).
liver cancer (1 paper, 2020). An epithelial or non-epithelial malignant neoplasm that arises from the liver. "We detected that liver cancer patients with low transcriptional levels of DPM1 (p = 0.007), DPM2 (p = 0.0032) and DPM3 (p = 0.029), were significantly connected with longer OS." (PMID 33282554, 2020).
Seizure (1 paper, 2022). A seizure is an intermittent abnormality of nervous system physiology characterized by a transient occurrence of signs and/or symptoms due to abnormal excessive or synchronous neuronal activity in the brain. "Seizures were present in most CDG patients, except in those with ALG12‐, DPM3‐, SRD5A3‐, and DPAGT‐CDG." (PMID 35279850, 2022).
tumor (3 papers, 2015 to 2024). "The highest mRNA expressions of DPM1/2 were observed in tumor stage 3, while the maximum DPM3 mRNA expression was noticed in stage 4." (PMID 33282554, 2020). "The maximum mRNA expressions of DPM1/2 were showed in tumor grade 4, whereas the supreme mRNA expression of DPM3 was found in tumor grade 3." (PMID 33282554, 2020). "These 6 tumor-exclusive proteins detected in every single sample comprised MARCKSL1, IKBIP, COPZ1, TIMP1, FAM50A and DPM3." (PMID 39681068, 2024).
brain disease (1 paper, 2022). "Thus, we conclude this new and pathogenic variant in DPM3 can lead to congenital muscle and brain disease." (PMID 35932216, 2022).
cancer (1 paper, 2020). A tumor composed of atypical neoplastic, often pleomorphic cells that invade other tissues. "In order to explore the gene expressions of three subunits of DPMS in different types of cancer, mRNA expressions of DPM1, DPM2 and DPM3 were analyzed by UALCAN." (PMID 33282554, 2020).
DPM3 also shares sentences with these, for which no sentence is quoted: Stroke (2 papers); bladder cancer (1); cataract (1); congenital muscular dystrophy (1); fructose intolerance (1); glioblastoma multiforme (1); liver disease (1); myopathy (1); neuroblastoma (1); Parkinson disease (1); prostate tumor (1); Walker-Warburg syndrome (1).